PDHA1 (pyruvate dehydrogenase E1 subunit alpha 1)
Diseases named in the same sentence as PDHA1 in open-access papers (continued):
Sharing a sentence is not in itself a finding about the gene and the disease.
schizophrenia (2 papers, 2020 to 2024). A major psychotic disorder characterized by abnormalities in the perception or expression of reality. "PDHA1 deficiency was first associated with schizophrenia in a report published in 201727, which described a patient with a mitochondrial disease due to a mutation in the PDHA1 gene who developed schizophrenia-like symptoms." (PMID 32404964, 2020). "In this study, we detected anti-PDHA1 antibody in sera from a subgroup of patients with schizophrenia." (PMID 32404964, 2020). "In the present study, MRI data revealed brain features in anti-PDHA1 antibody-positive patients that were different from those seen in ‘conventional’ schizophrenia." (PMID 32404964, 2020). "Anti-PDHA1 antibody-positive patients with schizophrenia had increased volumes of the left occipital fusiform gyrus compared to both healthy controls (p = 0.017) and antibody-negative patients (p = 0.009)." (PMID 32404964, 2020). "Further research is required to reveal the pathophysiology in the subgroup of schizophrenia with anti-PDHA1 antibodies." (PMID 32404964, 2020). "Anti-PDHA1 antibodies have been found in the sera of patients with schizophrenia, pointing to the mitochondrial dysfunction as a consequence that may underlie the pathogenesis of this condition." (PMID 39727940, 2024). "However, in contrast to ‘conventional’ schizophrenia, the anti-PDHA1 antibody-positive patients showed increased volumes in the fusiform gyrus; this aberrant pattern in regional brain volumes was also evident in the cuneus." (PMID 32404964, 2020). "This is the first report of an anti-PDHA1 antibody in patients with schizophrenia." (PMID 32404964, 2020). "The brain features of patients with schizophrenia whose sera reacted against PDHA1 differed from those without an immunological reaction." (PMID 32404964, 2020). "In our population, 3 out of 25 patients with schizophrenia presented immunoreactivity against the human recombinant PDHA1, whereas no participant showed an immunological reaction against human recombinant DLAT." (PMID 32404964, 2020). "Three patients with schizophrenia, but no controls, expressed antibodies targeting one of the candidate antigens, i.e., pyruvate dehydrogenase E1 component subunit alpha, somatic form, mitochondrial (PDHA1, EC 1.2.4.1), which is related to mitochondrial energy production." (PMID 32404964, 2020).
adrenocortical carcinoma (1 paper, 2022). "The genetic alteration of PDHA1 showed a poor prognosis in adrenocortical carcinoma (ACC) and KIRC patients and a good prognosis in LUAD patients." (PMID 36003495, 2022).
atherosclerosis (1 paper, 2024). A disease characterized by the build-up of fatty material and calcium deposition in the arterial wall resulting in partial or complete occlusion of the arterial lumen. "Inhibition of PDHA1 expression or activity can disrupt intracellular energy balance and potentially accelerate the progression of atherosclerosis." (PMID 39519014, 2024). "In early-stage atherosclerosis, genes such as ATP7A, GLS, DLD, ATP7B, and PDHA1 are highly expressed, whereas in later stages, the expression levels of FDX1, CDKN2A, SLC31A1, and MTF1 increase." (PMID 39519014, 2024).
B-cell NHL (1 paper, 2025). "PDHA1 was identified as a robust, independent, and consistent clinical predictor of OS in B-cell NHL patients." (PMID 41169526, 2025). "The development of copper-regulating genes (CRGs) signatures and the discovery of PDHA1 in cuproptosis regulation have the potential to enhance clinical decision-making for individuals with B-cell NHL." (PMID 41169526, 2025). "The findings suggest that PDHA1 may affect B-cell NHL prognosis by influencing the immune microenvironment and therapy sensitivity." (PMID 41169526, 2025).
bile duct cancer (1 paper, 2023). "Conversely, overexpression of PDHA1 and MPC1, along with PG-α, can counteract the Warburg effect and stimulate the proliferation of bile duct cancer cells." (PMID 38114959, 2023).
Burkitt lymphoma (1 paper, 2025). A rare form of malignant mature B-cell non-Hodgkin lymphoma. "Immunohistochemistry analysis revealed that PDHA1 was overexpressed in DLBL, MCL, and Burkitt lymphoma tissues compared to normal node tissues." (PMID 41169526, 2025). "PDHA1 is a potential antitumor target for treating DLBCL, MCL, and Burkitt lymphoma." (PMID 41169526, 2025).
cardiac hypertrophy (1 paper, 2020). "Fatty acid oxidation (Acadm, Etfdh, Acadl, Acadvl, Eci1, Hadh, Phyh, Acaa2, Hadha, Hadhb, Cd36), glucose metabolism (Dld, Pdha1, Pgam1, Pgam2, Acss1, Ldhb, Fh1, Slc2a4, Aldh6a1), TCA cycle (Aco2, Dld, Fh1, Ogdh, Sucla2, Sdha, Idh3b, Idh2) were up-regulated by hispidulin in cardiac hypertrophy." (PMID 33324687, 2020).
Cerebellar atrophy (1 paper, 2020). Cerebellar atrophy is defined as a cerebellum with initially normal structures, in a posterior fossa with normal size, which displays enlarged fissures (interfolial spaces) in comparison to the foliae secondary to loss of tissue. "However, in patients carrying PDHA1 mutations, cerebral atrophy, when present, was always associated with cerebellar atrophy." (PMID 33092611, 2020).
cognitive decline (1 paper, 2021). "In conclusion, our study illustrates the important role of PDHA1 in learning and memory, and it may be a potential target in the treatment of cognitive decline." (PMID 34720870, 2021).
COVID-19 (1 paper, 2023). A disease caused by infection with severe acute respiratory syndrome coronavirus 2. "In COVID-19 samples, the expression of PDHA1 was significantly higher compared to control samples, while the difference in PDHB expression between COVID-19 and control samples was not statistically significant." (PMID 37533853, 2023). "And the results of proteomics showed that the expression levels of PDHA1 and PDHB were significantly increased in COVID-19 patient samples." (PMID 37533853, 2023).
Dilater cardiomyopathy (1 paper, 2024). "The remaining pathways were all detected with a predominance of control proteins, such as the Citrate cycle (TCA cycle) (P-value < 0.0001; ACLY, DLST, PDHA1, PDHB), except Dilater cardiomyopathy (DCM) (P-value = 0.0006; ACTB, ADCY8, LOC396781, TPM1)." (PMID 38409238, 2024).
esophageal adenocarcinoma (1 paper, 2022). A malignant tumor with glandular differentiation arising predominantly from Barrett mucosa in the lower third of the esophagus. "Similarly, the increased expression of HSPH1, IDH3G, NUDT7 and PDHA1 was associated with shorter OS in the subgroup of patients suffering from esophageal adenocarcinoma (EAD)." (PMID 36298586, 2022).
ethylmalonic encephalopathy (1 paper, 2017). "Selected examples are cases with ethylmalonic encephalopathy (ETHE1), Niemann–Pick disease type C2 (NPC2), and pyruvate dehydrogenase E1-alpha deficiency (PDHA1)." (PMID 27848944, 2017).
Fanconi anemia (1 paper, 2023). Fanconi anemia (FA) is a hereditary DNA repair disorder characterized by progressive pancytopenia with bone marrow failure, variable congenital malformations and predisposition to develop hematological or solid tumors. "On the contrary, the cell cycle, the Fanconi anemia and protein export pathways, DNA replication, and homologous recombination were enriched in the high PDHA1 expression group." (PMID 38062233, 2023). "In addition, the cell cycle, the Fanconi anemia and protein export pathways, DNA replication, and Homologous recombination are enriched in the PDHA1 expression group." (PMID 38062233, 2023).
glaucoma (1 paper, 2023). Increased pressure in the eyeball due to obstruction of the outflow of aqueous humor. "Hence, the increased expression of PDHA1 (subunit of PDH) seems to have a great significance on the CDR1-induced RGC neuroprotection ex vivo and also highlights the relation between the pathogenesis of glaucoma and phosphoprotein cell signaling." (PMID 37509196, 2023).
lymphoma (1 paper, 2025). A malignant (clonal) proliferation of B- lymphocytes or T- lymphocytes which involves the lymph nodes, bone marrow and/or extranodal sites. "PDHA1 activation may enhance oxidative phosphorylation, leading to increased oxygen consumption and reduced lactate production in lymphoma cells." (PMID 41169526, 2025).
metastatic prostate carcinoma (1 paper, 2026). A carcinoma that arises from the prostate gland and has spread to other anatomic sites. "This study demonstrates that PDHA1 expression is found to be elevated in primary tumors from patients with metastatic prostate cancer." (PMID 41724793, 2026).
osteoarthritis (1 paper, 2024). A noninflammatory degenerative joint disease occurring chiefly in older persons, characterized by degeneration of the articular cartilage, hypertrophy of bone at the margins and changes in the synovial membrane. "Additionally, five genes related to cuproptosis (FDX1, LIPT1, PDHA1, PDHB, and CDKN2A) are considered candidate biomarkers or therapeutic targets for osteoarthritis synovitis." (PMID 39360273, 2024).
ovarian tumor (1 paper, 2022). "Pyruvate dehydrogenase E1 subunit alpha 1 (PDHA1) is reduced dramatically in cisplatin (DDP)-resistant SKOV3 and DDP-resistant ovarian tumor tissues, whereas miR-21-5p is considerably enhanced as compared to controls." (PMID 36338993, 2022).
papilloma (1 paper, 2022). A benign epithelial neoplasm that projects above the surrounding epithelial surface and consists of villous or arborescent outgrowths of fibrovascular stroma. "The mRNA levels of prolyl 4-hydoxylases-1 (Pdha1) and -2 (Pdha2), the key enzymes in collagen biosynthesis, were also significantly downregulated in Itga11−/− papillomas." (PMID 36003785, 2022).
paroxysmal dystonia (1 paper, 2020). "Three patients with PDHA1 mutations (3/7: 43%) and three with PDHX mutations (3/5: 60%) are under ketogenic diet with clearly beneficial effects on childhood-onset epilepsy or paroxysmal dystonia." (PMID 33092611, 2020).
stomach adenocarcinoma (1 paper, 2022). "However, for stomach adenocarcinoma (STAD), the downregulated PDHA1 expression predicted a good prognosis in patients." (PMID 36003495, 2022).
Thiamine deficiency (1 paper, 2024). Thiamine deficiency is a condition that occurs due to not enough thiamine (vitamin B1). "However, a study showed that thiamine deficiency reduces mRNA levels of the enzyme transketolase and the component E1-subunit beta of the PDH, but no alteration was observed in PDHa1 and OGDH genes in three human cell types." (PMID 39364430, 2024).
tumor (115 papers, 2015 to 2025). "Surprisingly, IDH2R140Q mutation changed the expression patterns of cupropotosis-associated genes, including FDX1, LIAS, LIPT1, DLD, DLAT, and PDHA1, which indicated that the sensitivity of tumor cells to cuproptosis depends on the types of genetic mutations." (PMID 40384935, 2025). "High levels of PDHA1 were thought to be associated with a better prognosis for lung cancer patients and can be used as a biomarker for the tumor microenvironment." (PMID 36882769, 2023). "Nevertheless, the detailed role of PDHA1 in cancers and the underlying mechanism driving tumor pathogenesis are still largely unclear." (PMID 36003495, 2022). "However, IF assays indicated that the tumor stages were positively associated with PDHA1 expression and negatively associated with CD56 expression in the NB tissues." (PMID 38012558, 2023). "Genetic ablation of pyruvate dehydrogenase A1 (Pdha1) in PTEN −/− tumors inhibited tumour growth, and this was associated with the reduced expression of lipogenic genes, which were components of a gene network regulated by sterol regulatory element-binding transcription factor (SREBF)." (PMID 34660272, 2021). "We next tested the growth of tumor cells containing the hypomorphic alleles of PDHA1." (PMID 34749809, 2021). "Moreover, we confirmed PDHA1 phosphorylation in human FH-deficient tumours." (PMID 29191787, 2018). "Interestingly, PDHA1 was shown to associate with the grades of tumor differentiation." (PMID 28076853, 2017). "In order to comprehend the molecular physiological functions of the GLS and PDHA1 genes in the LUSC tumour microenvironment, their localization in LUSC was determined." (PMID 41050056, 2025). "Subsequent comparison of tumour versus normal tissues revealed significant dysregulation: GLS expression was significantly reduced in tumours, while PDHA1 expression was elevated (Wilcoxon p < 0.01)." (PMID 41050056, 2025). "Utilising these findings, we have further elucidated the cell-specific expression patterns of GLS and PDHA1 in the tumour microenvironment of lung squamous carcinoma by employing single-cell sequencing technology." (PMID 41050056, 2025). "In this study, we sought to explore the potential impact of changes in the expression of cuproptosis-related genes, GLS and PDHA1, on the tumor microenvironment and immune response." (PMID 41050056, 2025). "Initially recognized as a key gene in cuproptosis, PDHA1 plays a pivotal role in the reprogramming of glucose metabolism in tumor cells." (PMID 41357210, 2025). "Recent studies have demonstrated that pyruvate dehydrogenase E1 subunit α1 (PDHA1) is a pivotal cuproptosis gene that is imperative for the reprogramming of glucose metabolism in tumour cells." (PMID 41050056, 2025). "The results demonstrated that the GLS gene exhibited elevated levels of expression in cancer cells and immune cells (including T cells, B cells, and dendritic cells), while the PDHA1 gene demonstrated comparatively reduced levels of expression in tumor cells." (PMID 41050056, 2025). "These alterations to the pathways suggest that there is enhanced immunogenic potential in tumours with the high GLS/low PDHA1 expression profile." (PMID 41050056, 2025). "Differential expression between normal tissues and BRCA tissues at each tumor stage was found in almost all cuproptosis-associated genes; however, only LIPT1, DLAT, PDHA1, and CDKN2A were differentially expressed among tumor stages." (PMID 39432636, 2024). "Elevated levels of genes like DLAT, FDX1, and PDHA1 correlate with poor outcomes, greater tumor aggressiveness, and immune suppression." (PMID 39867656, 2024). "In cholangiocarcinoma, SIRT3 plays a tumor-suppressive role by downregulating the HIF1α/PDK1/PDHA1 pathway, leading to tumor regression." (PMID 39620228, 2024). "Recent studies have proposed that PDHA1, a key cuproptosis gene, is crucial for reprogramming glucose metabolism in tumor cells." (PMID 39300580, 2024).
tumor (continued). "The mRNA level of PDHA1 in NB tissues was found positively correlated with the tumor stages through qRT-PCR." (PMID 38012558, 2023). "Except for LIAS and PDHA1, the expression levels of the remaining eight markers were statistically different between tumor and normal samples." (PMID 37190215, 2023). "The results revealed that tumor tissue in higher stages expressed higher PDHA1 and lower CD56, indicating increased tumor proliferation and decreased NK cell infiltration." (PMID 38012558, 2023). "The tumor samples were then divided into PDHA1-high (n = 15) and PDHA1-low (n = 65) groups according to the relative intensity." (PMID 37006250, 2023). "The genes LIPT1, PDHA1, and PDHB are responsible for encoding the lipoic acid pathway, which has been found to have significant implications in tumor progression." (PMID 38114959, 2023). "Compared with normal tissues, the expression level of PDHA1 in tumor tissues was significantly lower (p < 0.001)." (PMID 37006250, 2023). "On the one hand, the PDHA1-encoded pyruvate dehydrogenase complex plays an important role in energy metabolism, and the expression level of PDHA1 is closely associated with cell proliferation and energy metabolism in some cancers, suggesting that it may promote tumor growth and metastasis." (PMID 37006250, 2023). "Low levels of FDX1 and PDHA1 expression were observed in tumor tissues that had high levels of CD8 infiltration." (PMID 36895378, 2023). "Even in different studies on the same tumor, different investigators considered FDX1 and PDHA1 as risk or protective factor respectively." (PMID 36882769, 2023). "The Cancer Genome Atlas (TCGA), GEPIA2, and cBioPortal databases were utilized to elucidate the function of PDHA1 in 33 tumor types." (PMID 36003495, 2022). "The PDHA1 expression was negatively correlated with tumor-infiltrating immune cells, such as myeloid dendritic cells (DCs), B cells, and T cells in pan-cancers." (PMID 36003495, 2022). "Regarding p-PDHA1 in tumorigenesis, si-PDHA1 and reconstituted PDHA1 S293A dephospho-mimetic while reconstituted PDHA1 WT and S293D restored tumor growth with 4T1 cells in xenograft experiments." (PMID 35740278, 2022). "The GEPIA2 tool was also used to analyze the relationship between the PDHA1 expression and tumor pathological stage." (PMID 36003495, 2022). "Consistent with other studies, our analysis indicated that PDHA1 is an independent prognostic factor for OS and has a positive correlation with histological type and tumor size." (PMID 36497253, 2022). "By utilizing multiple bioinformatics tools, we carried out a systematic analysis of the prevalence and predictive values of PDHA1 in multiple tumor types." (PMID 36003495, 2022). "Butyrate induces hyperacetylation of PDHA1 to relieve the inhibition of PDHA1 phosphorylation at serine 293 to promote tumor cell apoptosis." (PMID 35990673, 2022). "Meanwhile, a large majority of cuproptosis-associated genes including FDX1, LIAS, DLD, DLAT, PDHA1, and GLS, were significantly associated with the tumor microenvironment (immune, stromal, and estimate scores) (p < 0.05)." (PMID 36105090, 2022). "We further assessed the differential expression of PDHA1 between tumor and normal tissues by matching TCGA and GTEx in several cancers." (PMID 36003495, 2022). "The heatmap showed that PDHA1 had a strong correlation with fourteen tumor functional statuses in most cancer types." (PMID 36003495, 2022). "Recent studies have proposed that pyruvate dehydrogenase E1 component subunit alpha (PDHA1), a cuproptosis-key gene, is crucial to the glucose metabolism reprogram of tumor cells." (PMID 36003495, 2022). "Here, we explored the potential correlation between PDHA1 expression and tumor-infiltrating immune cells by performing comprehensive research." (PMID 36003495, 2022). "We searched the CancerSEA website to verify the expression of PDHA1 at the single-cell level in different cancers and its relationship with the tumor functional status." (PMID 36003495, 2022).